CRP (C-reactive protein)
Diseases named in the same sentence as CRP in open-access papers (continued):
Sharing a sentence is not in itself a finding about the gene and the disease.
tumor (continued). "Univariate analysis of risk factors for OS age, BMI, tumor diameter, tumor differentiation, pTNM stage, carcinoembryonic antigen (CEA), CRP level, PNI, postoperative complications, and postoperative adjuvant chemotherapy were significant relevant factors." (PMID 35079325, 2022). "Postoperative CRP and leukocyte levels normalized, highlighting the relationship between the tumor and the inflammatory status." (PMID 36013476, 2022). "As expected, the inflammation marker CRP increased in the blood samples post-tumor resection (CRP [ng/ml]; mean ± SD; pre: 18.1 ± 24.6; post: 59.6 ± 42.5; p = 0.0046), reflecting the surgical insult." (PMID 35184226, 2022). "CRP can promote tumor cell invasion and metastasis through the activation of integrin α2 signaling in the inflammatory microenvironment." (PMID 35317078, 2022). "On multivariate analysis, LDH, CRP, tumor type, and ambulatory status proved to be independent predictors of survival." (PMID 35626151, 2022). "CRP can be produced by cells within the tumor microenvironment including stromal cells and mesenchymal-like tumor cells." (PMID 36177015, 2022). "High levels of CRP reflect an inflammation process in patients with infection and also in reactive inflammation in ongoing tumor growth." (PMID 35157721, 2022). "Independently of tumour stage, patients with higher plasma CRP levels were found to show significantly lower overall survival than those with lower levels of CRP." (PMID 35174082, 2022). "Multivariate analysis showed that CRP level (p < 0.001) and tumor size (p < 0.001) remained independent predictors of oncological events." (PMID 36358634, 2022). "In parallel, CRP was elevated in the post- versus pre-tumor resection samples, an anticipated effect due to tissue damage and wound healing processes after the surgical insult." (PMID 35184226, 2022). "As a standard, LDH, CRP, albumin, hemoglobin and platelets (all components of the LabBM score) must be available and in addition, the added value of a given tumor marker is studied in a multivariable model." (PMID 36531068, 2022). "Interleukin-6 (IL-6) and C-reactive protein (CRP) are the most studied to date and have been associated with larger tumor size, metastasis, and mortality in CRC patients." (PMID 36361914, 2022). "In this study, we found that serum CRP level was associated with UICC stage, tumor localization, T stage, N stage, and HPV infection." (PMID 35847918, 2022). "The present retrospective study investigated the impact of systemic inflammation on tumor progression using serum C-reactive protein (CRP) levels in a series of 87 surgically treated sporadic VS patients." (PMID 34882287, 2022). "Among them, leucine-rich alpha-2-glycoprotein (LRG1), complement component C9 (C9), and C-reactive protein (CRP) showed significant positive correlations with tumor size." (PMID 35806478, 2022). "The baseline characteristics classified by CRP showed significant differences in terms of age, sex, tumor stage, and BMI (all P<0.05)." (PMID 35752767, 2022). "Significant differences were observed in age, sex, tumor location, surgical procedure, operation time, and serum CRP level." (PMID 35079325, 2022). "A significant association was observed for CRP and AGR (CRP vs. tumor maximal dimension rho = 0.246, p = 0.030 and AGR vs. tumor maximal dimension rho = −0.263, p = 0.031)." (PMID 35629255, 2022). "Accordingly, serum levels of CRP correlate with the tumor mass in patients, with high levels of CRP reflecting advanced disease and poor prognosis." (PMID 36177015, 2022). "Nodal involvement, tumour location, level of CEA, CRP and CRP/lymphocytes ratio were significantly associated with OS among patients with any type of DM." (PMID 35740504, 2022). "In the subsequent Cox regression analysis, LDH (p = 0.007), CRP (p = 0.047), tumor type (p = 0.003), and ambulatory status (p = 0.010) maintained significance." (PMID 35626151, 2022).
tumor (continued). "C-reactive protein is increased in neoplastic diseases by tissue damage and promotes the inflammatory cascade." (PMID 36718344, 2022). "As a comparison, high AFP (>100 ng/mL) levels were associated with tumor size, vascular invasion, BCLC stages (p < 0.0001), and CRP (p = 0.0138)." (PMID 35053564, 2022). "The relationship between tumor response and occurrence of CRP-AFP model in patients treated with PD-1 inhibitors." (PMID 35185894, 2022). "Corresponding analysis revealed that sPD-L1 also correlated with CRP in the pre-tumor resection samples." (PMID 35184226, 2022). "A newly invented PRE-Stage was developed using a CRP–albumin–lymphocyte index < 3, central tumor location, and CA19-9 level > 40 U/mL, and it was able to significantly predict DSS and DFS when the patients were stratified into four stages (p < 0.05)." (PMID 35267414, 2022). "Significant differences were observed in age, body mass index (BMI), tumor diameter, tumor stage, pathological TNM (pTNM) stage, surgical procedure, intraoperative blood loss, and C-reactive protein (CRP) level." (PMID 35079325, 2022). "Western blot analyses were performed to assess the liver and corresponding tumor expression of inflammatory regulators, NF-κB, IL-6 and CRP, across the study groups." (PMID 36505796, 2022). "The patients who had increased baseline levels of CRP had a significantly shorter time-to-tumor progression than those with CRP levels within the normal range (< 3.14 mg/dl)." (PMID 34882287, 2022). "On univariate analyses, NLR, LDH, CRP, and clinical factors tumor type, ambulatory status, and sphincter function were significantly associated with survival." (PMID 35626151, 2022). "In the metastatic setting, elevated pre-treatment CRP and IL-6 were independently associated with shorter PFS and OS, and provided useful information on prognosis in addition to the tumor mutational status (RAS and BRAF)." (PMID 36233472, 2022). "Laboratory indicators such as red blood cells, hemoglobin, lymphocyte percentage, C-reactive protein, ferritin, albumin, and γ-glutamyl transpeptidase levels are also correlated with the tumor burden." (PMID 35013456, 2022). "First, we found that tumour M2-PK was significantly associated with DAS28-ESR and DAS28-CRP (a composite measure assessing the severity of RA), and ESR and CRP, which decreased after reduction in disease activity." (PMID 36059477, 2022). "More than half of our CRC patients were in stages II and III, and serum C-reactive protein (CRP) level slightly increased after tumor resection." (PMID 36076975, 2022). "The main inflammatory factors associated with tumours include interleukin 6 (IL-6), interleukin 10 (IL-10), interleukin 1β (IL-1β), tumour necrosis factor alpha (TNF-α) and C-reactive protein (CRP)." (PMID 36482346, 2022). "This concept led to the proposal of the CRP-to-albumin ratio (CAR) as a tool for assessing the extent of inflammation in a tumor microenvironment and, consequently, predicting prognosis." (PMID 35562926, 2022). "Our results showed that NLR, dNLR, PLR, LMR, SII, SIRI, and CRP were significantly altered in patients with higher tumor stages." (PMID 35629255, 2022). "The white blood cells, LDH, CRP, and alkaline phosphatase levels, blood chemistry, carcinoembryonic antigen, carbohydrate antigen 19-9, and alpha-fetoprotein tumor markers were all within normal limits." (PMID 36451465, 2022). "CRP is an indicator of inflammatory response, which combined with increased cytokines, growth factors, activated stroma, and DNA damage, promotes tumour invasion, migration and metastasis." (PMID 36184588, 2022). "RDW was positively associated with the levels of plasma inflammatory biomarkers (C-reactive protein, erythrocyte sedimentation rate, and interleukins), which are considered inflammatory tumor biomarkers." (PMID 35719922, 2022).
tumor (continued). "A statistically significant correlation was also demonstrated between high-serum CRP and the presence of vascular invasion, multiple tumors, tumor size, and the TNM stage." (PMID 36612251, 2022). "The CRP levels were determined by immunoturbidimetry, and the classical tumor markers (CEA and CA 19-9) were measured using CMIA (chemiluminescent microparticle immunoassay)." (PMID 35407400, 2022). "Because of the positive correlation between CRP levels and tumor size and NLR in baseline characteristics, propensity score matching was applied to eliminate the confounding effect." (PMID 35185894, 2022). "Low CXI was significantly associated with a more advanced tumor–node–metastasis (TNM) stage, a higher level of serum C-reactive protein, serum interleukin-6, and NLR, but also a decreased level of serum prealbumin and albumin." (PMID 36139560, 2022). "In this study, we found a significant association between elevated levels of the inflammatory marker CRP and recurrence of disease, especially recurrence of disease <6 months, which we defined as residual tumor." (PMID 36291945, 2022). "Activated endothelial cells allow platelets, neutrophils, and blood proteins (e.g., IL-6, IL1b, and CRP) to enter tissue to activate an anti-tumor response." (PMID 36612251, 2022). "Tumor and inflammatory markers (except CRP) correlated positively with GSSG, GSSG/GSH ratio, 8-oxodG and F2-IsoPs, and negatively with CAT and GSH." (PMID 36232966, 2022). "A Cox proportional univariate analysis confirmed that tumor size (p < 0.001), CRP level (p < 0.001), and LCR (p < 0.001) were significant prognostic factors." (PMID 36358634, 2022). "Polysaccharide fractions (coded as CRP) obtained from C. racemosa have been reported to show antitumor activity in tumor-inoculated mice (H22 tumor)." (PMID 35200631, 2022). "On univariate analyses, NLR (p = 0.033), LDH (p < 0.001), CRP (p < 0.001), tumor type (p < 0.001), pre-radiotherapy ambulatory status (p < 0.001), and sphincter function (p = 0.011) were significant." (PMID 35626151, 2022). "The C-index was 0.63 (95% CI 0.52–0.80) and indicates the probability that the baseline serum CRP value in a patient with a shorter time to tumor progression after surgery is higher compared to subjects with no or longer time to progression." (PMID 34882287, 2022). "In tumours, CRP is involved in the recruitment of monocytes/macrophages, a phenomenon that increases the complexity of the TME." (PMID 36159866, 2022). "In particular, the median ESR, CRP, and tumour M2-PK levels were highest in those with high disease activity." (PMID 36059477, 2022). "Previous studies have investigated the role of inflammation-based risk scores/ratios in advanced or metastatic NEN, noting the prognostic role of increased CRP and white blood cell counts, reflecting an inflamed tumor microenvironment." (PMID 36358883, 2022). "Secretion of acute proteins [such as C-reactive protein (CRP)] can promote tumor cell proliferation and support the growth of primary tumors, leading to the formation of a microenvironment conducive for metastasis and further secondary metastasis." (PMID 35464000, 2022). "In recent years, there have been several studies on using routine blood parameters as potential tumor prognostic markers, including C-reactive protein, albumin, neutrophil count, lymphocyte count and other leukocyte count." (PMID 34980025, 2022). "A ROC curve was constructed to determine a CRP cut-off value in the prediction of tumor progression." (PMID 34882287, 2022). "In HPV-positive group, the maximum tumor size, neoadjuvant chemotherapy and the body mass index (BMI) correlated significantly with C-reactive protein/albumin ratio (CAR)." (PMID 34992504, 2021). "Based on the literature database, there is no study comparing the diagnostic criteria for serum CXCL8 and CXCR2 levels with well-established tumor markers and CRP as GC biomarkers." (PMID 34680333, 2021).
tumor (continued). "Further, an association of systemic inflammation markers such as leukocyte, neutrophil and platelet counts as well as CRP levels with markers of the local tumor microenvironment and overall survival was reported." (PMID 33956203, 2021). "Concentrations of CRP, triglycerides and creatinine also increased with higher skin AF, while LDL-, HDL- and total cholesterol decreased across skin AF quintiles." (PMID 34176469, 2021). "Interactions between the tumor and host cells leading to systemic inflammation result in an acute-phase response characterized by the production of C-reactive protein (CRP) in the liver and increases in circulating proinflammatory cytokines." (PMID 34830921, 2021). "We also analyzed gene expression differences between groups divided by the CRP expression level in 24 HCC tumor tissues." (PMID 35070979, 2021). "We indicated that the highest SE from all tested parameters revealed CCR3 (68%) and this value is comparable to SE of C-reactive protein (72%) and higher than SE of commonly used tumor marker CA 19-9 (40%)." (PMID 34204490, 2021). "Serum CRP has been identified as a major player in prediction of survival in several tumour entities." (PMID 34887479, 2021). "OSCC patients with larger tumours and more advanced tumour stages have reduced overall survival when increased CRP levels are present." (PMID 33740951, 2021). "The AUCs for CRP, fibrinogen, and tumor size were 0.67 (95% CI: 0.59–0.76), 0.73 (95% CI: 0.64–0.82), and 0.65 (95% CI: 0.57–0.74), respectively." (PMID 34298854, 2021). "In univariate analysis, WHO PS ≥ 1, tumor stage IV, the presence of active brain metastases, ≥2 metastatic sites, ≥1 prior therapies, ALB < LLN, LDH ≥ ULN, CRP ≥ 2ULN, ALC < 750/mm3, and NLR ≥ 5 were associated with worse PFS (p ≤ 0.039)." (PMID 33418936, 2021). "The CRP/alb ratio is a novel inflammation-based prognostic score and has shown outstanding prognostic value in tumours such as those of the liver or lung." (PMID 33740951, 2021). "The composition ratio showed significant differences between urban and rural patients with different degrees of skin itching (P = 0.017); moreover, the difference of iPTH and hs-CRP levels were statistically significant (P = 0.009 and < 0.001, respectively)." (PMID 33471852, 2021). "Modern pharmacological studies have confirmed that nobiletin, an extract of CRP, has a wide range of pharmacological effects such as anti-tumor, anti-inflammation, and anti-oxidation." (PMID 33953786, 2021). "In the current study, we observed a correlation between high levels of inflammatory markers (NLR and CRP) and tumor expression of CA9 and SLC2A1, which further supports the interplay between hypoxia and inflammation in MPNST." (PMID 33810575, 2021). "Among them, inflammatory markers such as platelets, lymphocytes, C-reactive protein, and Glasgow prognostic have been used in the study of tumor prognosis." (PMID 34764993, 2021). "Proinflammatory mediators and tumor-infiltrating immune cells regulate serum levels of C-reactive protein (CRP)." (PMID 33672644, 2021). "Both elevated CRP and tumor marker levels represent indicators of a poor prognosis in resected PDAC patients." (PMID 33437015, 2021). "We determined BMI, NLR, CRP, perineural and neural invasion, and tumor size, all of which differed significantly between the two AAPR groups and were further engaged in the PSM procedure." (PMID 34746006, 2021). "Chemokines and their receptors and JAK-STAT signaling, both of which were associated with CRP/IL6 in our study, are involved in the inflamed immune cell–enriched tumor microenvironment." (PMID 34572592, 2021). "suspected that tumor cells produce CRP, which is thought to be the reason why patients with larger tumor volumes have higher CRP levels." (PMID 34211459, 2021).
tumor (continued). "Non‐CRP response would lead to earlier staging, and in the event of tumor progression, allow clinicians to administer alternative and more effective therapies while preventing exposure to potentially life‐threatening toxic effects of immunotherapy." (PMID 34925829, 2021). "In order to reveal pure effects of preoperative lymphocyte-to-CRP score for a survival outcome, a new trial is needed under matching patient’s tumor phenotypes between high and low score groups." (PMID 33507925, 2021). "Various studies indicate a correlation between the severity of the CRS and tumor burden, C-reactive protein (CRP) and ferritin levels, and cytokine levels." (PMID 34299273, 2021). "Along with tumor-related factors, including tumor size, number, and differentiation, several markers, including AFP, AFP-L3, DCP, CRP and NLR, were also associated with recurrence after curative therapies." (PMID 34638613, 2021). "Elevated CRP levels reflect an inflammatory response to tumor necrosis or local tissue damage, which are both factors that condition the stromal microenvironment for the engraftment and growth of metastases." (PMID 34064877, 2021). "Peritoneal exudate macrophages collected from mice given CRP/liposomes via intraperitoneal injection, did demonstrate anti-tumor activity and enhanced oxidative metabolism." (PMID 34552600, 2021). "Univariate analysis revealed four candidates (p < 0.10) for further multivariate regression: CRP/Alb (p = 0.053), preoperative fibrinogen (p = 0.014), tumor thrombus of IVC (p = 0.088), and distant metastasis (p = 0.020)." (PMID 34512814, 2021). "Our data highlight the importance of a comprehensive immune classification of tumors including players of innate immunity and support a role for CRP as an informative biomarker of the immune response taking place at the tumor site." (PMID 34531864, 2021). "Recent reports suggest that even in patients with advanced disease, elevated CRP levels correlate with tumor size and staging in NSCLC." (PMID 33534859, 2021). "In conclusion, we herein provide a framework for expanding our understanding of the immune landscape in CC and explore the role of CRP as a systemic and informative biomarker of the immune responses taking place at the tumor site." (PMID 34531864, 2021). "OS was significantly associated with ECOG PS (p=0.005), stage (p=0.014), gross tumor volume (p=0.004), baseline NRI (p=0.036), baseline C-reactive protein (CRP) level (p=0.003) and tumor response (p=0.000)." (PMID 34900709, 2021). "In our study, according to the univariate and multivariate analysis results, the clinical value of traditional HCC diagnosis and prognostic indicators such as tumor size/number, degree of differentiation, and inflammatory factors (CRP, NLR) have been verified." (PMID 34790226, 2021). "Tumor cells produce inflammatory cytokines, such as tumor necrosis factor α and interleukin (IL)-1 and -6, and IL-6 is a major stimulator inducing CRP synthesis." (PMID 34548054, 2021). "CRP/alb scores in OSCC patients have been considered as promising predictive markers for patients with OSCC in addition to tumour staging." (PMID 33740951, 2021). "In stage I–III CRC patients, the correlation analysis revealed that pretreatment CRP was positively correlated with sex and location of the primary tumor." (PMID 34765598, 2021). "We evaluated NS, BMI, body mass loss (BML) and albumin, total protein, CRP, CEA, CA19-9, lipase, amylase, tumor stage, and BC using bioelectrical impedance (BIA)." (PMID 34898583, 2021). "Regarding C-reactive protein (CRP), a study showed that elevated CRP, an acute phase protein, was correlated closely with portal vein tumor thrombus and distant metastasis in patients with HCC." (PMID 34733791, 2021). "Also, the level of preoperative serum CRP levels may serve to facilitate preoperative risk assessment and help to improve informed treatment decisions, especially in borderline decisions for well- and intermediately differentiated tumours." (PMID 34887479, 2021).